GOLGA6L4 (golgin A6 family like 4)
Tractability: PROTAC: ubiquitination databases record sites on it.
Gene: Protein-coding gene on chromosome 15 (84,235,773 to 84,245,358, forward strand). Ensembl gene ENSG00000184206.
Homologues: Paralogues in human: GOLGA6L10 (87% identical), GOLGA6L9 (74% identical), GOLGA6L6 (25% identical), GOLGA6L22 (25% identical), GOLGA6L1 (25% identical), GOLGA6L26 (25% identical), GOLGA6L2 (24% identical), GOLGA6L24 (24% identical), GOLGA6L25 (24% identical), GOLGA6L7 (23% identical).
Diseases named in the same sentence as GOLGA6L4 in open-access papers:
GOLGA6L4 is named in the same sentence as 3 diseases in open-access papers, as found by Europe PMC text mining. Sharing a sentence is not in itself a finding about the gene and the disease. The quoted sentences say what the papers report.
cervical adenocarcinoma (1 paper, 2021). An adenocarcinoma arising from the cervical epithelium. "We identified PIK3CA, NDN, GOLGA6L4, and BAIAP3 as SMGs in cervical adenocarcinoma and confirmed that NDN, GOLGA6L4, and BAIAP3 were novel SMGs." (PMID 33398034, 2021). "Fourth, in our study, after the evaluation of WES data in 20 cervical adenocarcinomas, six genes (i.e., PIK3CA, KRAS, TRAPPC12, NDN, GOLGA6L4, and BAIAP3) were predicted as driver genes that could promote tumor formation and development." (PMID 33398034, 2021).
GOLGA6L4 also shares sentences with these, for which no sentence is quoted: tumor (1 paper); viral infection (1).